IL10 (interleukin 10)
Diseases named in the same sentence as IL10 in open-access papers (continued):
Sharing a sentence is not in itself a finding about the gene and the disease.
colitis (continued). "Recent studies indicated that during acute DSS-induced colitis, there was induction in Th1 and Th17 cytokine profiles and that this converted into a Th2-biased (IL-4 and IL-10) inflammatory profile during the chronic stages of colitis." (PMID 21858153, 2011). "B. fragilis PSA has been shown to influence the special and temporal development of T cell responses during colonization of germ-free mice and it can protect against colitis by a mechanism involving the induction of regulatory T cells and IL-10 production." (PMID 21995674, 2011). "In animal studies, IL-10 -/- mice developed caecal inflammation when monoassociated with E. coli but distal colitis when colonized with Enterococcus faecalis." (PMID 21966525, 2011). "These TLR-dependent innate immune responses seemed to be important in the Il10−/− mouse colitis model in order to adapt to luminal bacteria and their antigens." (PMID 20671959, 2010). "In the gut, IL-10 is a key molecule for the induction of T regulatory cells and prevention of mouse colitis." (PMID 20498715, 2010). "Overall, these results demonstrate that mast cells protect Il10−/− mice against the development of spontaneous colitis." (PMID 20808919, 2010). "CD4cre mice have significantly fewer CD4+FoxP3+ Tregs in blood and IL10-expressing CD4+ T cells in the MLN on day 7 of DSS colitis in comparison to WT mice." (PMID 20537136, 2010). "The colitis in Il10−/− mice on the C57BL/6J background is mild to moderate, compared with when theIl10 tm1Cgn allele is bred into the 129/SvEv, C3H/HeJBir, or C3H.SW background strains, where colitis is severe and progressive." (PMID 20671959, 2010). "A regulatory role for PPARα in inflammation was first shown by the prolonged duration of inflammation in Ppara−/− mice, and network analysis identified Ppara as a key mediator gene decreased in expression during colitis in Il10−/− compared to C57 mice." (PMID 20671959, 2010). "For example, a mixture of probiotic strains (VSL#3) ameliorates Th1-mediated murine colitis by inducing TGF-β-bearing Tregs and also suppresses diabetes development in NOD mice by inducing IL-10-producing cells in gut associated lymphoid tissues (GALT)." (PMID 20126401, 2010). "The aim of this study was to determine if administration of cis-UCA would be effective in attenuating colitis and the possible role of IL-10." (PMID 21060867, 2010). "Here, we show that most Il10−/− mice developed moderate colitis already by 8.5 weeks of age and severe colitis peaking between 10 and 12 weeks of age when compared to 7-week-old Il10−/− mice." (PMID 20671959, 2010). "It will be important to examine how aberrant modulation of TLRs contributes to initiation and progression of colitis-associated neoplasia in the context of IBD-associated gene deficiency, such as IL-10." (PMID 20803699, 2010). "In contrast to acute C. rodentium-induced colitis, chronic spontaneous typhlocolitis develops in IL-10−/− mice colonized with Helicobacter spp.." (PMID 20976045, 2010). "Several aspects of innate and adaptive immune responses were affected at the gene expression level before (7 weeks of age) and after (12 weeks of age) colitis onset in Il10−/− mice." (PMID 20671959, 2010). "According to recent results it seems likely that increased secretion of IL-10 participates in protection from colitis after transfer of CD4+ T cells from CpG-ODN-treated donors." (PMID 21188217, 2010). "To observe the fluorescence images of the colitis mucosa with NBD-PZ, we used mouse models of acute colitis, which is induced by TNBS or DSS, and chronic colitis, which is induced in IL-10-deficient mice." (PMID 20074376, 2010). "Others have shown that Il10−/− mice develop increased gut permeability prior to development of colitis." (PMID 20808919, 2010).
colitis (continued). "As in colitis, intestinal irradiation represses IL-10 and all strategies that interfere with irradiation-induced NF-κB activation restore the IL-10 level, including 5-ASA treatment (unpublished results)." (PMID 20037741, 2010). "The experiments presented here provide evidence that a break in small intestinal barrier function is necessary for colitis to occur in the IL10−/− mouse." (PMID 18829978, 2009). "We recently demonstrated that TLR/MyD88 signalling to the NF-κB transcriptional system is critical for commensal bacteria-induced colitis in IL-10−/− mice." (PMID 19841748, 2009). "Histological evaluation showed that Il10−/− mice colonized with B. vulgatus developed moderate colitis (average score = 1.6) compared to WT mice (average score = 0.36)." (PMID 19551144, 2009). "Colitis progression in IL-10-/- mice closely corresponds with increased SAA levels (≥ 250 μg/ml) and with reduction in body weight, compared with the initial body weight." (PMID 18533024, 2008). "Recently, our laboratory showed that spontaneous colitis in IL-10-/- mice is driven in part by antigens (Ags) conserved in Mycobacteria." (PMID 18533024, 2008). "Recently, we reported that humoral and cellular responses during spontaneous colitis in IL-10-/- mice are driven in part by conserved Ags in Mycobacterium species." (PMID 18533024, 2008). "While additional studies will be required to ascertain the precise role of Mycobacteria in the induction and progression of colitis, we report that live mycobacterial challenge accelerates chronic colitis in IL-10-/- mice." (PMID 18533024, 2008). "Several cellular mechanisms that drive spontaneous colitis also mediate Mycobacteria-enhanced colitis in IL-10-/- mice." (PMID 18533024, 2008). "It is plausible that Mycobacteria stimulate TLRs to promote colitis in IL-10-/- mice, which presents a scenario where mycobacterial recognition via TLR and MyD88 activate DCs to control Th1 polarization and expansion." (PMID 18533024, 2008). "The present study dissects some of the common cellular and molecular mechanism that drive Mycobacteria-mediated and spontaneous colitis in IL-10-/- mice." (PMID 18533024, 2008). "In short, colitis was more aggressive in IL-10-/- mice that received live Mycobacteria, than compared to similar mice that received heat-killed bacilli or vehicle, housed under specific pathogen-free housing." (PMID 18533024, 2008). "Previously, we have shown that serum Mycobacteria-specific IgG2a Ab responses were higher in IL-10-/- mice with spontaneous colitis, than compared to control mice." (PMID 18533024, 2008). "To further address the adaptive versus innate leukocyte subsets responsible for Mycobacteria-enhanced colitis in IL-10-/- mice, we next assessed myeloid and plasmacytoid DC phenotypes from MLN, PP, and LP after disease onset." (PMID 18533024, 2008). "IL-10-/- mice develop spontaneous colitis that has similarities to human CD at ~3 months of age under conventional housing conditions which can be abrogated by anti-CXCL10 Ab treatment." (PMID 18533024, 2008). "DSS-exposed, luteolin-fed mice demonstrated more severe colitis than control-fed animals, whereas spontaneous colitis in IL-10−/−;NF-κBEGFP mice was significantly attenuated." (PMID 17611628, 2007). "Surprisingly, IL-10 and IFNβ expressions were also up-regulated during colitis induction and were down-regulated upon probiotic-pulsed DC treatment." (PMID 17375199, 2007). "It has also bean shown that IL-10 gene therapy is therapeutic for dextran sodium sulfate-induced murine colitis." (PMID 17069659, 2006). "Administration of recombinant human IL-10 to colitis patients is being evaluated as a therapeutic option in colitis patients." (PMID 16803619, 2006). "The clinical significance of IL-10 expression is supported by studies showing that immune-augmentation of IL-10 prevents inflammation and mucosal damage in animal models of colitis and in human colitis." (PMID 16259632, 2005).
colitis (continued). "On the other hand, IL-10 gene transfer technology has been used with some success in models of colitis, however its efficacy is variable." (PMID 16259632, 2005). "Based on modern advances, recombinant anti-inflammatory cytokines (i.e. IL-10) treatment is now being developed for experimental colitis and human IBD." (PMID 16259632, 2005). "The anti-inflammatory effect of adenoviral IL-10 gene transfer to mice was analyzed in experimental colitis induced by feeding of oral 3% dextran sulfate (DSS, MW~40–50 kD) over the course of 10 days, and body weight recorded daily." (PMID 16259632, 2005). "Colonization of an isolated Faecalibaculum rodentium has shown it could mitigate colitis in Il10−/− mice." (PMID 41378888, 2026). "We hypothesize that, in particular, the enhanced IL-10 secretion prevented colitis in Rag-/- mice that received Foxp3creCREBfl/fl CD4+ T cells." (PMID 40777015, 2025). "Indeed, the specific ablation of the il10 gene in Treg (Foxp3+ CD4+) cells results in spontaneous colitis, highlighting the fact that IL-10 produced by Treg is fundamental in maintaining tolerance, particularly in intestinal tissues." (PMID 41155360, 2025). "Notably, 19.6% of Il10−/−/Gsta4−/− mice spontaneously developed colitis and, occasionally dysplasia, while housed in an SPF environment, supporting key roles for anti-inflammatory and antioxidative genes in protecting against CRC." (PMID 39819335, 2025). "Similarly, Bacteroides fragilis attenuates DSS-induced colitis in mice through the TLR-2/IL-10 signal pathway." (PMID 39699251, 2025). "Given that the NF-κB pathway is downstream of cGAS/STING signaling, we hypothesized that LGG may induce IL-10 expression in a STING/NF-κB-dependent manner in the context of colitis." (PMID 39895628, 2025). "Interestingly, in comparison to SPF mice, colitis was attenuated in both sham- and E. faecalis-colonized Il10−/−/Gsta4−/− mice." (PMID 39819335, 2025). "Studies have demonstrated that up-regulating the expression of IL-10 could effectively mitigate DSS-induced colitis." (PMID 40806121, 2025). "To determine whether the differential tissue distribution of indirubin extends beyond DSS‐induced colitis, we evaluated its effect in IL‐10 knockout mice, which spontaneously develop colitis by 6–12 weeks of age." (PMID 40546113, 2025). "Moreover, upon the deletion of NOD2 in IL-10/mice, a remarkable improvement in the symptoms of colitis was observed." (PMID 40692778, 2025). "In addition, the expression of AhR targeted genes (CYP1A1, IL-10, and IL-22) was enhanced in colon of colitis mice through treatment with pasteurized A. muciniphila or Amuc_1100." (PMID 41488633, 2025). "The results suggested that miR-223 could alleviate colitis by coordinately suppressing pro-inflammatory cytokine production and enhancing IL-10-mediated anti-inflammatory signaling." (PMID 40799643, 2025). "This analysis aimed to characterize the microbial composition and diversity, and to determine whether A muciniphila or its culture supernatant could restore microbial balance in IL-10−/− mice with colitis." (PMID 41333470, 2025). "Similarly, oral NDGA administration attenuated the progression of IL-10 knockout-induced colitis, as evidenced by improved body weight and clinical colitis scores." (PMID 40596758, 2025). "For instance, macrophages produce IL-10 after LPS stimulation and in a mouse model of colitis." (PMID 39895628, 2025). "In IL10-knockout mice with spontaneous colitis, elevated expression of IFNG-AS1 was noted." (PMID 40658679, 2025). "For this, partial least squares discriminant analysis (PLS-DA) was used on the fecal relative abundance profiles of all bacterial taxa as observable variables and the remaining time of the corresponding IL-10-/- mouse to the first appearance of colitis symptoms as the predicted variable." (PMID 39843997, 2025).
colitis (continued). "Quantifying GLP-1+ cells in 4 mouse models of ileitis and colitis and characterizing 2 independent cohorts of each TnfΔARE mice and IL-10-/- mice, we found a consistent reduction in GLP-1-expressing cells confined to the site of active disease and correlating to the degree of inflammation." (PMID 41047099, 2025). "After gavage with DSS in piglets, compared with those in the CT group, the serum levels of IL-6 and IL-8 significantly increased (p < 0.05), whereas the level of IL-10 significantly decreased (p < 0.05), indicating that the colitis model in piglets was successfully established." (PMID 40362046, 2025). "IL-10−/− mice developed mild colitis as indicated by the disease activity index." (PMID 40732952, 2025). "IL-10−/− mice have been widely used to investigate IBD because they develop colitis spontaneously." (PMID 40732952, 2025). "Additionally, activating GPCR109A with SCFAs boosts anti‐inflammatory factor production, stimulates regulatory T‐cell activity, and fosters the development of IL‐10‐producing T cells, crucial for colitis prevention." (PMID 39830908, 2025). "In addition, this finding is consistent with a previous report that B cells mitigate colitis through an IL-10-independent pathway." (PMID 39543372, 2025). "Further investigations have revealed that L. johnsonii could activate intestinal CD206+ macrophages, thereby promoting IL-10 secretion and alleviating colitis." (PMID 40292216, 2025). "The ability to predict experimental colitis development for individual IL-10−/− mice could make this IBD mouse model easier to handle and manipulate for functional and mechanistic microbiome studies." (PMID 39843997, 2025). "The dominance of Lactobacillus johnsonii in HP group correlates with its unique capacity to polarize resident macrophages toward an immunoregulatory CD206+ phenotype and mediates IL-10 secretion via the TLR1/2-STAT3 signaling axis to ameliorate experimental colitis." (PMID 41154565, 2025). "In the colitis model, IL-10 increases were detected at early time points (days 11 and 15), whereas our study evaluated later stages (weeks 5 and 12), revealing a transient early increase that did not persist, underscoring the influence of experimental design on immunological outcomes." (PMID 41614846, 2025). "Similarly, NTBF outer membrane vesicles (OMVs), which are rich in PSA, activate TLR2-mediated IL-10 production, enhancing the generation of Tregs to prevent experimental colitis." (PMID 40292216, 2025). "The data demonstrated that miR-223 supplementation could mitigate DSS-driven colonic inflammation by dampening pro-inflammatory pathways while enhancing IL-10-mediated resolution, further supporting its therapeutic potential in colitis." (PMID 40799643, 2025). "Here, we study the relationship of IBD, biological clock, and gut microbiota based on the interleukin (IL)-10-/- mouse model for experimental colitis, using altered (4 h/4 h) light–dark cycles and (8 h night) time-restricted feeding (TRF) to disrupt and restore circadian rhythmicity." (PMID 39843997, 2025). "However, minimal colitis is observed in either Gsta4−/− or Il10−/−/Gsta4−/− mice following colonization with E. faecalis." (PMID 39819335, 2025). "LGG triggers an IL-10–based autocrine regulatory loop in monocytes during colitis." (PMID 39895628, 2025). "Collectively, these findings suggest that NDGA may offer protection against colitis induced by DSS treatment and IL-10 deficiency." (PMID 40596758, 2025). "Interestingly, LGG induction of monocytic IL-10 was specific to colitis, and LGG had little effect on IL-10 expression in mice without DSS treatment." (PMID 39895628, 2025). "Oral citrulline treatment improved CDI colitis and restored the colonic human IL10 mRNA expression." (PMID 39923847, 2025).
colitis (continued). "As such, ocrelizumab-induced colitis is believed to be a consequence of B cell depletion, particularly Bregs, with subsequent reduction of IL-10 secretion, which leads to uninhibited Th1 cell activity and predisposes the patient to diminished anti-inflammatory responses." (PMID 39974366, 2025). "Administration of T. spiralis crude larval antigen extract before induction of colitis reduced colitis severity as demonstrated by reduced colon weight-to-length ratio, improved macroscopic and microscopic scores, increased colonic IL-10 expression, and diminished colonic MPO protein expression." (PMID 40830617, 2025). "Compositional changes and reduced rhythmicity of the fecal microbiota preceded colitis and could predict colitis symptoms for individual IL-10-/- mice across different experiments." (PMID 39843997, 2025). "GUT−108 displayed comparable establishment in the gut of germ-free IL10-/- mice and modulation of host immune function while also reducing inflammatory cytokine expression in humanized IL10-/- mice with induced colitis, showing its potential for clinical application." (PMID 41239968, 2025). "Motivated by these emerging insights, we hypothesized that LGG might induce IL-10 in specific intestinal myeloid cells to prevent colitis." (PMID 39895628, 2025). "Indeed, a recent paper utilizing a strain of E. coli known to increase IL‐10 macrophages demonstrated an amelioration of DSS colitis in mice." (PMID 40509652, 2025). "Additionally, the in vivo function of ITLN1 regulation on inflammation, PANoptosis, and the intestinal mucosal barrier was explored in interleukin-10 knockout (IL-10 KO) colitis model mice." (PMID 40520022, 2025). "In summary, O. splanchnicus modulated the immune landscape of the colon under inflammatory conditions, and neutrophils might be involved in its protective effect in both acute DSS‐induced colitis and Il‐10−/− spontaneous colitis mouse models." (PMID 40990446, 2025). "CW supplementation inhibits the high levels of inflammation induced by DSS, suppressing excessive inflammatory mediators (serum TNF‐α, IL‐1β, and IL‐6), downregulating the overexpressed mRNA levels of TNF‐α, IL‐1β, IL‐6, TLR4, and iNOS, while upregulating IL‐10, thereby alleviating colitis." (PMID 39830908, 2025). "Furthermore, hUC-MSCs increase the number of CD5+ Breg cells, which in turn suppress T cell proliferation and promote IL-10 production to protect against experimental colitis." (PMID 40433382, 2025). "Notably, the secretion and expression of anti-inflammatory factor IL10 were increased in the serum and colonic tissue of A. shahii-treated colitis mice." (PMID 39936902, 2025). "Collectively, the microbiota remodeling observed in our study is likely to act synergistically with the direct epithelial and immunomodulatory effects of A.m, thereby contributing to the attenuation of mucosal inflammation and the restoration of immune homeostasis in IL-10−/− colitis." (PMID 41333470, 2025). "In conclusion, while external clock disruption may promote experimental colitis in IL-10-/- mice, other factors appear to induce colitis even in the absence of external clock disruption." (PMID 39843997, 2025). "Hence, we cannot rule out an additional role for other myeloid subsets in LGG-induced IL-10 production during colitis." (PMID 39895628, 2025). "Given that mice were allowed a 2-day water recovery period after 7 days of DSS exposure, this elevation in IL-10 may reflect the initiation of a compensatory anti-inflammatory response during the early resolution phase of colitis." (PMID 40697820, 2025). "The TLR-2-mediated sensing of OMV-associated PSA was shown to ameliorate colitis severity in an experimental TNBS-colitis model, by increased induction of IL-10-producing Tregs, whereas cDC-derived IL-10 was elevated in a human in vitro system upon OMV exposure." (PMID 41028655, 2025).